BMP5 (bone morphogenetic protein 5)
Diseases named in the same sentence as BMP5 in open-access papers (continued):
Sharing a sentence is not in itself a finding about the gene and the disease.
ovarian carcinoma (1 paper, 2020). A malignant neoplasm originating from the surface ovarian epithelium. "We used the PrognoScan database to analyze the association of BMP5 expression with survival ratio of brain and CNS, breast, colorectal, lung and ovarian cancer patients." (PMID 31973134, 2020). "The database queried for the BMP5 gene mutations in 15,405 number of samples from 26 cancer studies of breast, colorectal, lung, bladder, and ovarian cancer." (PMID 31973134, 2020). "Then we performed distinct analysis for revealing the role of BMP5 in breast, bladder, colorectal, lung, and ovarian cancers." (PMID 31973134, 2020). "The multi-omics analysis revealed that BMP5 is down-regulated distinctively and is negatively correlated with clinical outcomes in breast colorectal, lung, and bladder, except ovarian cancer." (PMID 31973134, 2020). "To understand the role of BMP5 in cancer more definitely, we investigated the prognostic status of BMP5 in breast, bladder, colorectal, lung, and ovarian cancer." (PMID 31973134, 2020). "Pathway analysis of differentially co-expressed genes with BMP5 in breast, lung, colon, bladder and ovarian cancers revealed the BMP5-correlated pathways." (PMID 31973134, 2020). "For BMP5, a large number of positively-correlated genes were found in breast, colon, lung, bladder, and ovarian cancer." (PMID 31973134, 2020). "Our analysis on ovarian cancer represents the correlation between lower BMP5 mRNA expression and higher overall survival rate." (PMID 31973134, 2020). "It has been reported that BMP, together with its subtype BMP5, is involved in the initiation of several types of cancers such as colon, lung, breast, bladder, and ovarian cancer." (PMID 31973134, 2020). "High survival ratio was exhibited in low BMP5 expression group (n = 70 and 90, respectively) of ovarian cancer compared to the high expression group (n = 63 and 43, respectively), according to the DUKE-OC dataset." (PMID 31973134, 2020). "More to that, the analysis with the ONCOMINE and GENT database have shown that BMP5 expression was apparently down-regulated in multiple cancer types, which includes bladder, breast, colorectal, lung, and ovary cancers." (PMID 31973134, 2020). "But in ovarian cancer, low expression of BMP5 is positively correlated with overall survival." (PMID 31973134, 2020). "Use of prognostic analysis showed negative association of BMP5 down-regulation with four types of cancer except for ovarian cancer." (PMID 31973134, 2020).
papilloma (1 paper, 2018). A benign epithelial neoplasm that projects above the surrounding epithelial surface and consists of villous or arborescent outgrowths of fibrovascular stroma. "BMP5 expression was verified in mouse hyperplastic and dysplastic epidermis and epithelium of papilloma." (PMID 30546048, 2018).
polycystic ovary syndrome (1 paper, 2022). A disorder that manifests as multiple cysts on the ovaries. "Previous studies have shown that several BMPs, including BMP2, BMP4, BMP5, BMP6, BMP7 and BMP8A are expressed in the granulosa cells from normally cycling and polycystic ovary syndrome women." (PMID 35395768, 2022).
preeclampsia (1 paper, 2022). Preeclampsia is a hypertensive disorder of pregnancy that is characterized by new-onset hypertension with proteinuria presenting after 20 weeks of gestation, and depending on mild or severe forms may initially present with severe headache, visual disturbances, and hyperreflexia. "Another study utilizing another group of multiple preeclampsia gene sets showed mainly immune-related genes (bone morphogenetic protein 5 (BMP5), cell surface glycoprotein (CD) 200R1 (CD200R1) and 28 (CD28), and TLR7) that are differentially expressed in preeclampsia." (PMID 35269385, 2022).
rectal cancer (1 paper, 2025). A primary or metastatic malignant neoplasm that affects the rectum. "This study identified a TRP channel-related gene signature (BMP5, DHRS11, GLTP, NFE2L3, and TMCC3) that predicts rectal cancer prognosis and modulates tumor–immune crosstalk." (PMID 40963625, 2025).
Sleep apnea (1 paper, 2025). An intermittent cessation of airflow at the mouth and nose during sleep is known as sleep apnea. "Furthermore, the craniofacial and bone related genes had high posterior probability for associating only for sleep apnea (BMP5, PP = 0.99; COL11A2, PP = 0.98)." (PMID 41332830, 2025).
type 2 diabetes (1 paper, 2025). "Overall, more studies, beyond single-cell transcriptomics, are needed to investigate further the potential causality of altered BMP5 expression in the development of beta cell failure in type 2 diabetes." (PMID 40471239, 2025). "We then determined BMP5 expression in our scRNA-seq dataset of primary human islets (from non-diabetic donors) untreated or treated with beta cell stressors associated with the development of type 1 and type 2 diabetes." (PMID 40471239, 2025). "Taken together, these data show that BMP5 signalling is enhanced in beta cells in type 2 diabetes and upon ER stress and inflammation." (PMID 40471239, 2025). "BMP5 and its target genes are upregulated in beta cells from donors with type 2 diabetes." (PMID 40471239, 2025). "We assessed the expression of BMP5 in publicly available single-cell RNA sequencing (scRNA-seq) datasets of primary human pancreatic islet cells from donors with or without type 2 diabetes, or islets exposed to stress conditions." (PMID 40471239, 2025). "Next, we assessed the expression of BMP5 in beta cells from donors with type 2 diabetes (17 donors, 7344 cells) or non-diabetic control donors using the publicly available scRNA-seq dataset." (PMID 40471239, 2025). "The apparent discrepancy with the original paper describing this dataset, which did not report alterations in BMP5 expression in beta cells derived from type 2 diabetes donors, may be attributed to a difference in computational analysis." (PMID 40471239, 2025).
tumor (32 papers, 2014 to 2026). "Crucially, we uncovered a novel immunoregulatory cascade: OSMR drives BMP5 transcriptional activation, orchestrating N2-polarization of tumor-associated neutrophils (TANs) and upregulating PD-L1 expression on TANs, ultimately impairing CD8+T cell cytotoxicity." (PMID 41653653, 2026). "This evidence suggests that BMP5 has an anticancer action and, therefore, that its decline has a role in tumor transformation, as well as in EMT, and then in the loss of epithelial markers." (PMID 32722068, 2020). "Examination of publicly available databases revealed that BMP5 mutation is also found in several other tumor types." (PMID 30572883, 2018). "Based on public databases and our clinical samples, the consistency of loss of BMP5 at DNA, RNA and protein level confirmed its importance and tumor suppressor role in CRC." (PMID 30572883, 2018). "Implant of HT-29 cells in mice revealed that expression of WT BMP5 reduced the tumor size and tumor weight as compared to BMP5-deficient control group (P < 0.0001), whereas the tumor inhibition effect weakened in MUT BMP5 group though the difference is statistically significant (P < 0.001)." (PMID 30572883, 2018). "Fib-BMP5 was found mainly in the tumour samples, and was characterized by the elevated expression of SLC14A1, NRG1, and WNT5A." (PMID 41281745, 2025). "The results indicated a consistent decrease in BCL2 and BMP5 expression in most tumor samples, while PSMB8 and PSME2 showed increased expression." (PMID 41403941, 2025). "Gene expression analysis found downregulation of BMP5 in tumor tissues versus normal adjacent tissues; the data are in agreement with those from the GEPIA database." (PMID 34073426, 2021). "Seventy-nine hub genes co-expressed with BMP5 were identified, and their functions were enriched in cell migration and tumor metastasis." (PMID 34745928, 2021). "Metastatic lymph nodes (n = 122) showed even lower BMP5 expression (average IHC score = 4.49) than primary tumor." (PMID 34745928, 2021). "The average IHC score of BMP5 protein expression in primary tumor (n = 93) was 5.27, which was lower than the score in adjacent normal tissues (n = 93, average IHC score = 6.02)." (PMID 34745928, 2021). "Overall, BMP5 expression was higher in adjacent normal tissues than primary tumor tissues and was the lowest in metastatic lymph nodes." (PMID 34745928, 2021). "Based on the co-expression network of BMP5, 79 hub genes were selected, and their functions were enriched in cell migration and tumor invasion." (PMID 34745928, 2021). "BMP5 has an essential function in COAD initiation and development, as it is a tumor suppressor gene mutated in around 7% of the cases." (PMID 34073426, 2021). "We found that LHX2, BMP-5 and GDF11 had complex interactions with other missing proteins and BMP-5 had both tumor suppressing and tumorigenic roles." (PMID 32050622, 2020). "In fact, BMP5 was identified as a tumor suppressor in sporadic CRC and the loss of BMP5 happening at early stages of CRC was linked to the poor survival of patients." (PMID 33123277, 2020). "In this investigation, we aimed to determine the difference of BMP5 expression and genetic alteration in seven tumor types." (PMID 30572883, 2018). "In summary, the finding of common alterations in BMP5, together with functional data indicating its effect on cell growth and migration, suggest that BMP5 is an important tumor suppressor in human CRC." (PMID 30572883, 2018). "Further analysis in paired samples found only the fold change (Log2(Tumor/Normal)) of E-cadherin was correlated with that of BMP5." (PMID 30572883, 2018). "Here, we reported that by exome sequencing and public data analysis, bone morphogenetic protein 5 (BMP5) was identified as a novel tumor suppressor gene in sCRC, and its downstream genes was characterized by RNA sequencing." (PMID 30572883, 2018).
tumor (continued). "GREM1 and the BMP ligand BMP5 were enriched significantly in the stromal fraction, in keeping with the results from the mouse model, whereas tumour cells expressed BMP4 in several cases." (PMID 27492255, 2016). "These immunohistochemical data suggest that tumor cells expressing BMP5 and BMP6 induce the transformation of mesenchymal cells, which normally express BMP2 and BMP4, in preosteoblasts and osteoblasts." (PMID 25529855, 2014). "Our findings establish OSMR as a molecular linchpin connecting intrinsic tumor survival pathways (PI3K/CCNE2) with extrinsic immunosuppressive reprogramming (BMP5/TANs/CD8+T cells), providing a clinically actionable target to overcome treatment resistance in GC." (PMID 41653653, 2026). "Among BMPs, BMP5 has been reported to play tumor-suppressive roles." (PMID 35054776, 2022). "A qRT-PCR validation step was conducted in a COAD patient cohort comprising of 29 tumor tissues and 29 normal adjacent tissues, endorsing the expression level for BMP5, as well as for two of the miRNAs targeting key EMT related genes, revealing upregulation of miR-27a-5p and miR-146a-5p." (PMID 34073426, 2021). "BMP5 is not in the top 20 frequently mutated genes, but is overexpressed in tumor tissue and correlated with overall survival rate, as our data showed." (PMID 34073426, 2021). "The loss of BMP-5 expression takes place as an early event in CRC where BMP-5 may dysregulate E-cadherin and then trigger tumor initiation and development." (PMID 32050622, 2020). "(B)Correlation of fold change (Log2(Tumor/Normal)) between BMP5 and EMT markers." (PMID 30572883, 2018). "The tumor suppressor role of BMP5 highlights its crucial role in CRC initiation and development." (PMID 30572883, 2018). "We also found miR-32 and miR-655 could partially reverse the tumor inhibition ability by stable BMP5 expression in SW480 cells." (PMID 30572883, 2018). "To test whether loss of BMP5 is common in cancer, we firstly verified the protein level of BMP5 in seven tumor types using immunohistochemistry (IHC)." (PMID 30572883, 2018). "The blots of tumor proliferation biomarker PCNA confirmed BMP5 could affect HT-29 and SW480 cell growth." (PMID 30572883, 2018). "(C) Correlation between BMP5 and E-cadherin in six tumor types." (PMID 30572883, 2018). "We further validated the tumor inhibition impact of BMP5 in CRC both in vitro and in vivo." (PMID 30572883, 2018). "In the tumor-to-tumor signaling direction, activin receptor type-2B (ACVR2B) was implicated in three of the fifteen top-scoring interactions with corresponding ligands of bone morphogenetic protein 5 (BMP5), growth differentiation factor 11 (GDF11), and inhibin beta C chain (INHBC)." (PMID 36676129, 2023). "However, the levels and role of BMP5 can differ among tumours." (PMID 32968094, 2020). "BMP5, a member of the TGF-β superfamily, has tumor-suppressive effects on colorectal carcinogenesis." (PMID 40963625, 2025). "BMPs required for the formation of new bone include BMP-5 and BMP-6, which are expressed by tumor cells." (PMID 36415832, 2022). "Among 11 BMPs, BMP3 and BMP8A expression levels were upregulated, and 5 BMPs (BMP2, BMP5, GDF5, BMP6, and GDF10) downregulated in tumor tissues compared with normal tissues." (PMID 34745928, 2021). "Last, the correlation among eight deBMPs/BMPRs was analyzed in tumor tissues of TCGA-LUAD, BMP5, and GDF10, as prognostic factors were well correlated with other deBMPs/BMPRs." (PMID 34745928, 2021). "Then we compared the expression of each member in ccRCC tissues and corresponding noncancerous normal tissues, unfortunately we found that BMP4, BMP5, and BMP7 expression was lower in tumor tissues." (PMID 31155610, 2020). "Our study detected the up-regulation of BMP-5 in liver samples of HBx mice, and these livers had fibrosis but no tumor formation." (PMID 32050622, 2020). "Low expression of BMP5 correlates with patients’ poor survival, which is not significant in other 6 tumor types." (PMID 30572883, 2018).
tumor (continued). "Furthermore, BMP5 expression was positively correlated with E-cadherin in CRC patients and its dysregulation play a vital role in epithelial-mesenchymal transition (EMT), thus triggering tumor initiation and development." (PMID 30572883, 2018). "Notably, BMP5 negative expression and its prognostic value is uniquely significant in sCRC but not in other tumor types." (PMID 30572883, 2018). "Bmp5+ lobular-like fibroblasts and Cd36+ committed preadipocytes were not present within tumors, while Acta2 (α-SMA)+ myCAFs presented new tumor clusters not found in hyperplastic glands (Fig. EV5H,I)." (PMID 40216939, 2025).
cancer (24 papers, 2009 to 2025). A tumor composed of atypical neoplastic, often pleomorphic cells that invade other tissues. "One study reported that 13 cases of BMP5 mutation across seven cancers where gastrointestinal cancers (GICs) were the most influenced by recurrent hotspot mutations." (PMID 31973134, 2020). "In our analysis, we found diverse missense and truncating mutations in the BMP5 protein-coding sequence while exposed to cancer cells." (PMID 31973134, 2020). "Together, these results establish BMP5 as a key regulator of basal prostate stem cell homeostasis and identifies a potential therapeutic approach against Pten-deficient cancers." (PMID 32894216, 2020). "Furthermore, we detected 143 variants in 66 cancer-associated genes, including BMP5, with the highest predicted deleteriousness score of 22.7, MET and USP44." (PMID 34069790, 2021). "In light of these results, we hypothesized that BMP5 signaling may contribute to the maintenance of Pten-deficient cancer stem cells." (PMID 32894216, 2020). "Here, we identify the ligand BMP5 as prime driver of Pten-deficient cancer progression." (PMID 32894216, 2020). "As conveyed by these results, BMP5 could be associated with certain key signaling pathways related to cellular proliferation, differentiation, metabolism and post-transcriptional control corresponding to cancer progression." (PMID 31973134, 2020). "Pre-CAFs exhibited a high expression of genes like PDGFRA, POSTN, BMP2, BMP5, CEBPB, and BICC1, associated with the serrated pathway of CRC and cancer progression." (PMID 39456726, 2024). "Of these eight PRS genes, three (BMP5, TNFRSF11B, and IGFBP2) are immune-related genes, and their association with the prognosis of cancer patients has been previously reported." (PMID 35535221, 2022). "Previous studies showed that BMP5 overexpression inhibited cancer cell growth and arrested cells in the G1-phase of the cell cycle, thereby implying that BMP5 induced senescence by inhibiting the cell cycle." (PMID 33744859, 2021). "Forty differently expressed genes (DEGs) were commonly up-regulated with BMP5 in five selected cancers derived from the Venn diagram." (PMID 31973134, 2020). "We conducted cDNA microarray analysis by using the ONCOMINE database to explore the gene expression of BMP5 in cancer types." (PMID 31973134, 2020). "To study the expression and evaluation of BMP5 as a potential prognostic value for the treatment of various cancers, we systematically analyzed the BMP5 expression and its clinical outcomes in certain cancers." (PMID 31973134, 2020). "According to the analysis using the GENT database, the average expression of BMP5 was lower in cancer tissues than in the normal tissues." (PMID 31973134, 2020). "Overall, our analysis has shown that BMP5 was significantly down-regulated in several cancer datasets." (PMID 31973134, 2020). "A Pan-Cancer Analysis highlighted that gene alteration in TGF-β pathway was carried by 39% cancers, especially gastrointestinal (GI) cancer, and BMP5 was one of the 6 recurrent hotspot mutations in GI cancers." (PMID 33123277, 2020). "Herein, the results showed that BMP5 expression was down-regulated in several cancer types including bladder, brain, breast, colon, kidney, liver, lung, ovary, pancreas, prostate, stomach, testis, and thyroid." (PMID 31973134, 2020). "We summarized the prognostic value of BMP5 mRNA expression in various cancers by using the patient prognosis data from databases with significant Cox p-values (p <0.05)." (PMID 31973134, 2020). "To determine the role of BMP5 in cancer, we have explicitly evaluated the expression pattern of genes in the cancers." (PMID 31973134, 2020). "Hierarchical clustering of expression fold-change values of BMP5 and 11 functional protein partners in 6 different cancers provides an overview of functional correlation." (PMID 31973134, 2020).